CXCR4 (C-X-C motif chemokine receptor 4)
Diseases named in the same sentence as CXCR4 in open-access papers (continued):
Sharing a sentence is not in itself a finding about the gene and the disease.
tumor (continued). "Taken together, these data demonstrate high expression of CXCR4 in WM cells harboring the MYD88 L265P cases independent of the CXCR4 mutational status and show high expression of genes associated with CXCR4 signaling and tumor growth particularly in CXCR4Mut cases." (PMID 33669329, 2021). "Thus, activation of the SDF-1/CXCR4/AKT pathway is important for tumor metastases and progression." (PMID 34220311, 2021). "Knockdown of CXCR4 expression level via applying a CRISPR/Cas9 genome editing system in CRC cells could inhibit tumor angiogenesis triggered via IGF1R with the help of SDF-1 in the tumor microenvironment." (PMID 33768092, 2021). "Similarly, blocking CXCR4 actions with an antagonist (CTCE-9908) in PC3-Bcl-2 cells in a xenograft model exhibited a decreased tumor size, which was associated with suppressed VEGF expression, angiogenesis, and lymphangiogenesis in the tumor microenvironment." (PMID 32585812, 2020). "We hypothesized that CXCR4-mediated chemotaxis could be involved in the immunological response to these treatments, which would likely be accompanied by an increase in CXCR4 density within the tumor." (PMID 31802362, 2020). "Furthermore, tumor irradiation might have resulted in increased recruitment of CXCR4-positive T lymphocytes at the tumor site as a result of the acute immune response to treatment-induced cell damage." (PMID 31802362, 2020). "In addition, our Western blotting results showed increased CXCR4 expression in tumor colonocytes compared to matched adjacent normal-appearing colonocytes, and were in agreement with Ottaiano and colleagues’ findings of increased CXCR4 in malignant colonocytes as assessed by immunostaining." (PMID 32110952, 2020). "In addition, these specific anti-tumor actions of Calebin A further correlated with inhibition of cell metastatic (CXCR4, MMP-9) and proliferative (cyclin D1) biomarkers, all of which are known to have a NF-κB binding site in their promoters, thus promoting their transcription." (PMID 32708030, 2020). "Most importantly, a recent Phase I/II clinical trial with the reversible CXCR4 inhibitor plerixafor – a strategy named Macrophage Exclusion after Radiation Therapy or MERT – in conjunction with chemoirradiation improved local control of tumor recurrence in newly diagnosed glioblastoma patients." (PMID 32014107, 2020). "Also, anti-miR-21 + sh-CXCR4 repressed xenograft tumor growth." (PMID 33123586, 2020). "In a preliminary bilateral tumor model, animals sequentially injected with biomarker-specific nanoprobes demonstrated preferential accumulation of target specific probes to their respective tumors: CXCR4 targeted probes to MCF7 cells and CAV1 targeted probes to 4175TR cells." (PMID 33172421, 2020). "Moreover, CXCR4 expression was significantly correlated with tumor invasion and stage." (PMID 32232002, 2020). "Thus, targeting CXCR4 could be useful both to block CSCs and to decrease tumor microenvironment immune suppression." (PMID 33123122, 2020). "However, it was demonstrated that ACKR3, by forming heterodimers with CXCR4 and modifying CXCR4 signaling, may also promote tumor growth and/or metastasis." (PMID 32456359, 2020). "Of note, the reduction was more evident in hypoxia condition (p = 0.005, one-way ANOVA), indicating that the impact of reduced expression of the IGF2BP3/CD164/CXCR4 oncogenic pathway may be stronger in the tumor microenvironment compared to physiological conditions." (PMID 32719743, 2020). "Additionally, the interaction of CXCL12 with CXCR4 recruits MDSCs, and endothelial cells induce Tregs through TGF-β; both are implicated in the generation of the immunosuppressive tumour microenvironment." (PMID 32466214, 2020). "Therefore, CXCR4/CXCL12 axis is a significant target for tumor therapy." (PMID 33392074, 2020). "Furthermore, it is of interest to know if CXCR4 blockade can enhance tumor immunity." (PMID 33194719, 2020).
tumor (continued). "In addition, the SDF-1α/CXCR4 axis modulates tumor stem cells to initiate and promote lung cancer." (PMID 32344892, 2020). "However, the CXCR4 inhibition affects osteoclastogenesis and enhances tumor growth in the bones." (PMID 33096815, 2020). "In conclusion, our findings reported that double-targeted knockdown of miR-21 and CXCR4 could more effectively inhibit the proliferation, migration, invasion, and growth of transplanted tumor and promote cell apoptosis, which were involved in the PI3K/AKT and Raf/MEK/ERK signaling pathways." (PMID 33123586, 2020). "Moreover, CXCL12/CXCR4 axis plays an important role in tumor growth and metastasis." (PMID 33392074, 2020). "To assess whether the CXCR4 positive cells have the features of the tumor-initiating cells, we compared the mRNA expression levels of stemness-associated markers such as NANOG, OCT4, LIN28, and SOX9 between CXCR4 positive and negative cells by quantitative real-time PCR." (PMID 32232002, 2020). "Besides, interference of TUG1 attenuated tumor growth by regulating miR-133b and CXCR4 in vivo." (PMID 32390763, 2020). "There appear to be two mechanisms by which CXCL12 affects tumor cell biology: 1) direct stimulation of signaling pathways that promote cancer cell growth, metastasis, and angiogenesis; 2) indirect effects, including the recruitment of CXCR4/CXCR7-positive cancer cells to CXCL12-expressing organs." (PMID 33363463, 2020). "This may induce overexpression of CXCR4 by tumor cells that attempt to avoid apoptosis." (PMID 31802362, 2020). "In addition, inhibition of CXCR4-mediated chemotaxis by the antagonist AMD3100 could have resulted in a reduction in the radiation-induced infiltration of CXCR4-expressing immune cells into the tumor." (PMID 31802362, 2020). "Interestingly, high CXCR4 expression in tumor tissue paralleled its expression in TAMs." (PMID 32943996, 2020). "Moreover, a previous nanoparticle related study published in 2018 demonstrated that combined delivery of Sorafenib with a mitogen activated protein kinase (MEK) inhibitor using C-X-C motif chemokine receptor 4 (CXCR4)-targeted nanoparticles reduced hepatic fibrosis and prevented tumor development." (PMID 32850829, 2020). "Additionally, a tumor-associated inflammatory mediator, prostaglandin E2 (PGE2), has demonstrated a role in controlling the expression and interactions of CXCL12 and its respective receptor, CXCR4, which are implicated in the process of tumor progression." (PMID 31354741, 2019). "Therefore, imaging of CXCR4 in these circumstances may benefit from longitudinal spatio-temporal data on tumor development/metastasis during estrogen deprivation therapy." (PMID 31652624, 2019). "Thus, the outcome of CXCR4 inhibition might differ depending on the tumor type or even individual patient." (PMID 30800123, 2019). "Hence, we hypothesized the involvement of CXCR4 signaling in controlling neutrophil motility and immune-tumor cell interactions involved in the initiation of early metastatic events and micrometastasis formation." (PMID 30787324, 2019). "However, anti-CXCR4 ADC may also target various cell types infiltrating the tumour microenvironment recruited through the CXCL12/CXCR4 pathway and that support tumour growth, such as bone marrow-derived mesenchymal, vascular and myeloid cells." (PMID 30792442, 2019). "Furthermore, HIF-1 could activate ERK and Akt pathways, upregulate the expression of VEGF, induce tumor angiogenesis, increase vascular permeability, and promote the metastasis of tumor cells by activating the expression of CXCR4." (PMID 30789971, 2019). "Taken together, our results showed that overexpressing CXCR4 in the intestine epithelial mucosa accelerates the tumorigenic process in inflammation-driven tumorigenesis, resulting in massive infiltration of inflammatory MDSCs and macrophages and increased tumor size and multiplicity." (PMID 30678736, 2019).
tumor (continued). "Thus a HA-based dermal filler loaded with CXCL12 can attract and trap CXCR4+tumor cells." (PMID 31332163, 2019). "SDF-1 expression was significantly induced in tumor and stromal cells, and an expansion of CXCR4-expressing CSCs was detected in PD/S-SCCs generated in immunocompetent mice, indicating that SDF-1 signaling may be activated in CSCs of advanced tumors independently of the immune status of the mice." (PMID 30874597, 2019). "Interestingly, in the brains bearing GL261 tumors, not only was CXCR4 phosphorylation increased in the tumor cells with CED, but there was also observably more p-CXCR4 in the surrounding parenchymal tissue, implicating neuroglial cells have a role in possibly other flow-related signaling." (PMID 31632905, 2019). "We also observed that the expression of CXCR4 was strongly downregulated in PB-NK cells as compared to autologous PF-NK cells as well as to HD-NK cells, suggesting a possible role of this chemokine receptor in the recruitment of CD56dim NK cells from the periphery to the tumor microenvironment." (PMID 31497016, 2019). "Our results indicate that functional crosstalk between PDGFR/SDF-1 signaling regulates tumor cell invasion and metastasis in human and mouse advanced SCCs, and suggest that CXCR4 and/or PDGFR inhibitors could be used to block metastasis of these aggressive tumors." (PMID 30874597, 2019). "Therefore, targeting CXCR4 on tumor cells and neutrophils could serve as a double bladed razor to limit cancer progression." (PMID 30787324, 2019). "Additionally, CXCR4 plays a crucial role in tumor through mediating cell adhesion." (PMID 30430424, 2019). "Therefore, inhibition of CXCR4 signaling could lead to impaired neutrophil motility and ability to respond to tumour cells also as a result of altered mmp9-driven chemotaxis." (PMID 30787324, 2019). "Increased expression of CXCR4 may be observed in specialized tumour niches." (PMID 31877673, 2019). "However, PDGFR and CXCR4 inhibition significantly reduced the invasion capability of hSCC11 PD/S cells, indicating that activation of both signaling pathways promotes tumor cell invasion in advanced SCCs." (PMID 30874597, 2019). "Interestingly, CXCR4+ tumor cells may have stem-like properties, a high metastatic potential, and show radiation resistance." (PMID 30813533, 2019). "However, multivariate analysis (including IRS values of SSTs, CXCR4 and CgA, Ki-67 levels, patient age, tumor grade, size and stage, tumor functionality, presence of lymph node or distant MTS), revealed SST2A expression and Ki-67 levels as the only independent prognostic factors for patient outcome." (PMID 30867449, 2019). "A second possible reason for discrepancy, which may be relevant for one of the three discordant cases, could be that the histology specimen was obtained 3 years before the CTC sample was taken, and the reduced CXCR4 expression seen in CTCs might have arisen from tumour evolution." (PMID 30636773, 2019). "Furthermore, as SDF-1/CXCR4 signaling induces tumor cell survival, autocrine activation of this signaling may promote migrating cell survival during dissemination or sustain the proliferation of these cells at the distant tissues." (PMID 30874597, 2019). "Therefore, CXCL12/CXCR4 interaction could be considered as an important driving force of MDSC recruitment into the tumor microenvironment." (PMID 30813533, 2019). "Interestingly, patients with G3 and PD tumours had nuclear CXCR4 staining only." (PMID 30636773, 2019). "Therefore, the anti-tumour activity of anti-CXCR4 ADCs might be enhanced in the bone marrow and in other organs with high CXCL12 expression." (PMID 30792442, 2019). "Therefore, targeting ACKR3 could prevent lymph node entry and distant metastasis of CXCR4+/ACKR3+ positive tumor cells." (PMID 30800123, 2019). "Hence, these data could open up CXCR4-targeted personalized therapeutics targeting CXCR4-positive tumor blood vessels." (PMID 31336612, 2019).
tumor (continued). "In view of the association of CXCR4 expression with HCC progression, we designed CXCR4-targeted NPs to co-deliver sorafenib and metapristone to CXCR4-expressing HCC, with the purpose of enhancing the synergistic anti-tumor efficacy and reducing the off-target toxicity." (PMID 31151472, 2019). "Therefore, it was conceivable that CXCR4 highly expressed vessels could support tumor survival by supplying nutrients and oxygen." (PMID 31336612, 2019). "Likewise, systemic treatment with a CXCR4 antagonist also significantly inhibited tumor growth." (PMID 30873179, 2019). "A reason why hearing disability is not always correlated with tumor dimensions could be an invasive growth pattern caused by CXCR4 overexpression in certain tumors." (PMID 31620068, 2019). "Thus, future immune-based strategies may be focused on combinations of different immune checkpoint inhibitors with substances targeting CXCL12/CXCR4 and reversal of local immunosuppression in the microenvironment, converting a ‘cold’ tumor into a ‘hot’ tumor." (PMID 30813533, 2019). "For example, CXCL12/CXCR4 axis is also of high interest for immunotherapeutical approaches due to its crucial role in tumor initiation and progression; therefore, possible future applications might include patient selection and therapy monitoring for targeted therapies." (PMID 30191351, 2018). "As an active biomolecular axis, SDF1/CXCR4 participates in a variety of physiological and pathological conditions, including hematopoiesis, embryonic development, cell chemotaxis, cell calcium influx, immune tolerance and inflammation as well as tumor proliferation and migration." (PMID 29783989, 2018). "In addition to mobilizing HSPC, the interference with the CXCR4-SDF1α axis has also been proposed as a possible strategy to “mobilize” malignant stem cells from their protective niche, thus rendering tumor stem cells more vulnerable to chemo- or irradiation therapy." (PMID 29382856, 2018). "Therefore, the present study aims to explore the CXCL12 and CXCR4 expression profile in local CRC patients and determine their association with various clinicopathologic factors such as age, tumour differentiation, angiolymphatic and perineural invasion, and their response to chemotherapy." (PMID 29887884, 2018). "Therefore, we postulated that TQ may modulate the expression of CXCR4 and inhibit tumor metastasis in vivo." (PMID 30564115, 2018). "In this study, we demonstrated that the CXCR4/CXCL12 pathway was upregulated in the primary tumor and in the matched macrometastatic SLNs of luminal B BC patients who had tumor recurrence, and it was associated with characteristics of tumor aggressiveness and invasiveness such as LN involvement." (PMID 29849822, 2018). "Although the receptor for CXCL14 is still unknown, it has been reported that CXCL14 is able to synergize with CXCL12 via allosteric modulation of CXCR4, and recruit myeloid DCs to the tumor sites, where it likely promotes their maturation to sustain antitumor immunity." (PMID 30591657, 2018). "Resveratrol is a specific inhibitor of NF-ҡB in different tumor cells; it can downregulate the nuclear localization of NF-ҡB phosphorylation and its acetylation, which cause attenuation of NF-ҡB-regulated gene products (MMP-9, CXCR4) involved in tumor-invasion and metastasis." (PMID 30584449, 2018). "Thus, CXCR4 is more likely to be a good indicator for tumor malignant behaviors." (PMID 29783989, 2018). "Therefore, it is reasonable to suppose that AnnexinA7 through the coordination of VEGFC/D-VEGFR3/NRP2, and SDF1/CXCR4 may affect the process of tumor development and progression." (PMID 29783989, 2018). "Some studies have revealed that SDF1 and CXCR4 are not only expressed in macrophages, hematopoietic cells, vascular endothelial cells, muscle cells, heart tissue, liver tissue, kidney tissue, brain tissue and skin tissues but are also expressed in many types of tumor cells." (PMID 29783989, 2018).
tumor (continued). "Therefore, released ubiquitin from the necrotic center/cells of a tumor might be the most important source for CXCR4 activation and might additionally influence the composition of the tumor microenvironment." (PMID 29721166, 2018). "In addition, a co‐expression was found between CD164 and CXCR4 in tumor tissues." (PMID 30022623, 2018). "Although the [68Ga]-Pentixafor-PET/CT revealed the probable primary tumor, the bioinformatics analyses of gene expression data could not support our assumption that CXCR4 expression and the mutation status of EGFR are linked." (PMID 29721166, 2018). "However, lower CXCR4 levels were observed in more advanced tumours." (PMID 29887884, 2018). "The utilization of CXCL12-CXCR4 during homing may also be difficult to target due the overlap in roles between tumor cell homing and HSC homing, as targeting DTCs using CXCR4 inhibition would also release HSCs from the niche, causing significant clinical adverse effects." (PMID 29642534, 2018). "As described in this section, SDF-1/CXCR4 signaling reportedly contributes to neoplastic transformation, malignant tumor progression, infiltration, metastasis, angiogenesis and vasculogenesis, and consequently therapy resistance of many different tumor entities." (PMID 30622535, 2018). "Therefore, modulation of the CXCL12/CXCR4 axis in NB tumors could impact multiple aspects of tumor pathogenesis, including immune dysregulation." (PMID 30149659, 2018). "Therefore, we hypothesized that combining anti-OX40 with CXCR4-antagonist will enhance the functionality of tumor-infiltrated effector cells as well as produce durable anti-tumor responses by augmenting immune memory." (PMID 30400835, 2018). "The expression of CXCR4 was mostly confined to the cytoplasmic membrane and cytoplasm of neoplastic cells whereas CXCL12 was mainly located to cytoplasm and, in a lesser extend to cytoplasmic membrane of tumor cells but also to tumor-associated macrophages and cancer-associated fibroblasts." (PMID 30012106, 2018). "Finally, the CXCL12/CXCR4 axis was constantly overexpressed in all passages in both tumours." (PMID 28386296, 2017). "The expression of SDF1α and CXCR4 has been strongly implicated in tumor growth, promoting cell migration and the recruitment of cells implicated in the revascularization process in tumors; this strongly suggested that SDF1/CXCR4 assists tumors in evading anti-angiogenic therapy." (PMID 28057017, 2017). "Besides its long-established role as a major co-receptor for HIV-1 viral entry and infection in CD4+ T-lymphocytes, CXCR4 is also involved in tumor cell growth, survival and metastasis of multiple types of human cancer, as well as several other diseases (e. g. inflammatory diseases, WHIM syndrome)." (PMID 28945785, 2017). "By this method, expression of CXCR4 could be detected in all tumor samples." (PMID 29088715, 2017). "Therefore, this experiment suggests that the amount of CXCR4 expressed in larger tumors may be involved reduced efficacy of tumor cells to bevacizumab treatment." (PMID 28057017, 2017). "Given to a tumor consists of heterogeneous cell populations, we could easily replace the binding domain of CXCR4-KLA with other ligands to target other CSCs that express different cell-surface biomarkers such as CD133, CD44, CD117, and MyD88 of OVC in the future." (PMID 28196146, 2017). "Moreover, a marked reduction in vascular endothelial growth factor (VEGF) expression, CD31+ blood vessels, CD4+ Foxp3+ Treg cells and the expression of MMP-2, MMP-9, MMP-13 and C-X-C motif chemokine receptor 4 (CXCR4) in the tumour stroma were observed in the Smad3−/− tumour microenvironment." (PMID 28262747, 2017). "In addition to TGFβ, CAFs release stromal cell-derived factor 1 (SDF-1/CXCL12), which recruits endothelial progenitor cells to the tumor site to facilitate angiogenesis and directly promote tumor growth via binding to its cognate receptor, CXCR4, expressed by cancer cells." (PMID 28467800, 2017).